PODXL (podocalyxin like)
Diseases named in the same sentence as PODXL in open-access papers (continued):
Sharing a sentence is not in itself a finding about the gene and the disease.
tumor (continued). "The role of PODXL in tumorigenesis remains unclear, but it has been demonstrated to promote the tumor growth, invasion and metastasis." (PMID 28881743, 2017). "Interestingly, in non-tumor regions of livers from treated rats, PODXL was weakly observed in hepatocyte nuclei." (PMID 26135398, 2015). "In I-type tumours, membranous PODXL in the metastasis was seen in 1/21 (4.8 %) cases denoted as having non-membranous expression in the primary tumour, and non-membranous PODXL expression in the metastasis was denoted in 2/3 (66.7 %) cases with primary tumours displaying membranous PODXL expression." (PMID 26028992, 2015). "Ectopic expression of PODXL enhances tumor aggressiveness in vitro." (PMID 25887862, 2015). "In addition, and importantly, we found that patients with I-type tumours displaying membranous PODXL had a beneficial effect of adjuvant chemotherapy." (PMID 26028992, 2015). "The herein presented results also indicate a beneficial effect of adjuvant chemotherapy on intestinal type tumours with membranous PODXL expression, suggesting the potential utility of PODXL as a biomarker for improved treatment stratification of these patients." (PMID 26028992, 2015). "Thus, the herein observed prognostic and potential predictive value of PODXL, in particular in I-type tumours, is of potential clinical relevance and merits further study in additional retrospective cohorts as well as in a controlled, prospective trial." (PMID 26028992, 2015). "Moreover, similar to the situation in colorectal and urinary bladder cancer, PODXL expression was observed predominantly on the invasive tumour front, also suggesting its importance in the metastatic spread of the disease." (PMID 26028992, 2015). "This may be due to a different cytoplasmic activity of PODXL in left- compared to right-sided tumours." (PMID 25004935, 2014). "We also show a difference in PODXL expression depending on tumour location." (PMID 25004863, 2014). "Membranous PODXL expression did not associate with age, gender, tumour location (right vs left hemicolon or colon vs rectum), or tumour histology." (PMID 25004935, 2014). "PODXL has been reported to promote tumor cell invasion through MMPs." (PMID 23596468, 2013). "Interestingly, in several samples, PODXL was differentially expressed in the tumor and PODXL staining was highest in the perivascular regions as well as in the pseudopalisading cells surrounding the necrotic areas." (PMID 24146797, 2013). "Although there was a discordance of PODXL expression between primary tumours and lymph node metastases in some cases, this was limited to a few cases with PODXL positive primaries where a clonal distribution of PODXL expression was observed in the metastatic lymph nodes." (PMID 23819542, 2013). "PODXL reportedly promotes the metastatic potential of tumor cells." (PMID 23596468, 2013). "Of the samples positive for PODXL, staining was diffuse throughout the tumor." (PMID 24146797, 2013). "A more comprehensive analysis of the correlation between PODXL mRNA and protein expression might be provided by performing microdissection of strongly staining areas from frozen tumour sections." (PMID 22769594, 2012). "However, the expression of PODXL in certain normal tissues poses a significant challenge; targeting this glycoprotein could lead to on-target, off-tumor effects, raising concerns about potential adverse side effects in non-cancerous cells." (PMID 40508013, 2025). "Consequently, PODXL has emerged as a promising candidate for targeted tumor immunotherapy." (PMID 40843679, 2025). "Therefore, PODXL has acquired increasing attention as a target of tumor immunotherapy." (PMID 38203331, 2023). "Importantly, PODO447 only recognizes this glycan in the context of a PODXL core protein poly-peptide as this epitope is not on any other tumor-associated sialomucins." (PMID 38188285, 2023).
tumor (continued). "Besides, tumor-associated glycoforms of conventional antigens, including SLAMF7, CLEC14A, PDPN, PODXL, and CD44, could also be ideal target antigens." (PMID 36261831, 2022). "In addition, PODXL overexpression activates CD16, a receptor involved in antibody-dependent cell cytotoxicity (ADCC), suggesting that PODXL may aid in tumour protection by impairing NK cell-mediated ADCC." (PMID 34201212, 2021). "Furthermore, NK cells may acquire PODXL from cancer cells by trogocytosis, a mechanism of intercellular transfer of membrane fragments and molecules from tumour cells to NK cells during close contact to modify the phenotype and function of immune cells." (PMID 34201212, 2021). "Recently, increasing evidences have suggested that PODXL was involved in multiple links in several process of tumor development, such as cell adhesion and morphology, lymphatic metastasis, tumor cells motility and invasiveness, tumor angiogenesis and prognosis." (PMID 32615943, 2020). "PODXL may act as tumor promotor and may serve as a potential target for antitumor therapy." (PMID 32615943, 2020). "Moreover, PODXL has been suggested to promote tumor growth, invasion, and metastasis; accordingly, high PODXL expression could have adverse effects on overall survival (OS), disease-specific survival (DSS), and disease-free survival (DFS) in several cancers." (PMID 29854293, 2018). "It is however noteworthy that the category of tumours with moderate-strong cytoplasmic staining (score 2) is a somewhat ambiguous group with an intermediate prognosis, undoubtedly harbouring some cases with a prognosis equally poor to cases with membranous PODXL expression." (PMID 26028992, 2015). "Incorporation of the purified protein (e.g., MUC16 or PODXL) into a lipid bilayer allows for its physiologically relevant orientation and provides a consistent binding interface, while eliminating the potential contribution of other selectin ligands present on the tumor cell surface." (PMID 26329844, 2015). "PODXL expression did not associate with age, gender, nor tumour location (colon vs. rectum)." (PMID 25004863, 2014). "The proportion of tumours with high PODXL expression was relatively small compared to the proportion in previous studies (5.7% vs. 7.9–13.4%) (, which could be explained by differences in antibody, patient series, staining methods, and staining evaluation/cut- off points." (PMID 25004863, 2014). "Moreover, since previous studies were retrospective and based on analysis of tissue-microarrays (TMAs), a secondary objective was to examine whether analysis of full-face sections reveals a larger proportion of tumours with membranous PODXL expression." (PMID 23819542, 2013). "Moreover, the finding of a higher proportion of PODXL positive tumours in full-face sections is of particular clinical relevance in stage II disease, where it is of uttermost importance to identify patients with high-risk disease who would benefit from adjuvant treatment." (PMID 23819542, 2013). "While this had been done for the majority of the here analyzed tumours, it should be pointed out that tumour areas denoted as having distinct membranous PODXL expression could not only be found at the invasive front, but also in scattered areas within the tumour." (PMID 22769594, 2012). "The oncogenic function of ADAR1 and tumor-suppressive functions of ADAR2 were shown, where editing of the PODXL gene by ADAR2 decreased tumorigenicity." (PMID 40852728, 2025). "The downregulation of cell adhesion proteins (ITGB1, LGALS3, LGALS3BP, SDCBP, PODXL, CDCP1) further suggests a potential impact on tumor cell attachment, migration, and invasion, contributing to the anti-metastatic effects of TSA." (PMID 40429900, 2025). "Primary tumor tissues of HGSC patients (n = 17) and one benign ovarian sample were analysed by immunohistochemistry for PODXL." (PMID 38553472, 2024).
tumor (continued). "PODXL, ezrin, and CLIC5 are colocalised in tumour regions of the rat liver, and PODXL and ezrin are present in immunoprecipitates of CLIC5." (PMID 34201212, 2021). "PODXL also took part in the NF-kB, PI3K/AKT, Hippo and MAPK/ERK signaling pathway, and facilitated tumor progression by increasing cell proliferation, migration and invasion as well as suppressing apoptosis." (PMID 32615943, 2020). "We investigated the abilities of PODXL, BCL7B, ARHGEF4, and ITGB1 to predict prognosis in PDAC in comparison with UICC TNM stage and tumor size." (PMID 31166991, 2019). "In the present study, we investigated the use of PODXL, BCL7B, ARHGEF4, and ITGB1 as useful markers for the prognosis of postoperative PDAC patients in comparison with tumor size and the TNM staging system." (PMID 31166991, 2019). "In conclusion, the combination of PODXL with ITGB1 and the combination of BCL7B with ITGB1 accurately predicted the postoperative prognosis of PDAC patients better than tumor size and the UICC TNM stage." (PMID 31166991, 2019). "Consistent with the functions of altered PODXL level on migration and invasion of GC cells in vitro, SGC7901 and AGS transfected with shPODXL significantly inhibited tumor growth in nude mice in comparison with the control group." (PMID 29748877, 2019). "Another weakness is that the assessment of PODXL expression in the pooled cohort was based on pre-neoadjuvant biopsies in the neoadjuvant group, and on TMA samples from the resected tumor in the surgery only group." (PMID 30355278, 2018). "This study examined the prognostic impact of PODXL and RBM3 expression in tumours from incident cases of UBC in a large, population-based cohort." (PMID 28293425, 2017). "Conversely, inhibition of PODXL decreases TAZ and TAZ downstream genes expression, and results in the suppression of tumor invasiveness, stemness, and sensitizing to chemotherapies." (PMID 28946619, 2017). "In cohort 1 and 3, the worst prognosis was seen in patients with tumours displaying high expression of both EGFR and PODXL." (PMID 27160084, 2016). "A quantitative analysis of receptor-ligand binding kinetics of functional selectin ligands expressed by metastatic tumor cells, such as MUC16 and PODXL, in the presence of shear flow will further the understanding of the metastatic process." (PMID 26329844, 2015). "Although we observed co-localization of EZR, CLIC5 and PODXL in HCC samples, this expression pattern in tumor cells was only found in the late stage of HCC." (PMID 26135398, 2015). "Tumours of the RHC were more poorly differentiated (p < 0.0001) and showed higher PODXL expression (p < 0.001)." (PMID 25004863, 2014). "Previously, the staining of PODXL in TMA-sections versus whole tissue was shown to be uniform, which eliminates the issue of investigating only a small proportion of the tumours by the TMA technique." (PMID 25004935, 2014). "High levels of PODXL expression have been reported in sinusoidal endothelial cells and tumour-like hepatic lesions, whereas adjacent non-tumorous liver tissues typically show little or no expression." (PMID 41462970, 2025). "PODO447 not only exhibited specificity against PODXL tumor cell lines, but also demonstrated no reactivity against normal primary human tissues, including PODXL kidney podocytes." (PMID 39186767, 2024). "Upregulation of PODXL correlates with tumour progression, invasion, and metastasis; however, the molecular form of PODXL synthesized by tumour cells contains highly sulfated KS chains and not the low-sulfation KS chains produced by normal embryonic stem cells." (PMID 38474072, 2024). "PODXL enhances the extravasation through direct binding to ezrin, a cytoskeletal linker protein, which enables the transition of tumor cells from a non-polarized, rounded cell shape to an invasive extravasation-competent morphology." (PMID 38203331, 2023).
tumor (continued). "Anti-PODXL mAbs, which recognize tumor-specific glyco-epitopes on PODXL but do not react with PODXL expressed on normal cells, have been developed." (PMID 38203331, 2023). "This suggests that a major role in vivo of PODXL is in tumor formation and metastasis rather than tissue tropism." (PMID 36735782, 2023). "As expected, PODXL protein was rarely expressed in normal tissues, and in addition, both ZO1 and E-cadherin levels were decreased in the CRC tissue compared to those in the non-tumor tissue." (PMID 34440856, 2021). "A link between membranous PODXL expression and clinically more aggressive tumours was further confirmed, but PODXL expression was not an independent prognostic biomarker in this study." (PMID 28293425, 2017). "Non-classic tumour types were significantly correlated with a more advanced higher T-stage (p < 0.001), grade (p < 0.001), membranous PODXL expression (p < 0.001) and low RBM3 expression (p < 0.001)." (PMID 28293425, 2017). "In cohort 2, high PODXL expression was an independent prognostic factor in patients with tumours displaying low but not high EGFR expression (unadjusted HR 2.02; 95 % CI 1.02–4.02) and adjusted HR 2.59; 95 % CI 1.26–5.31)." (PMID 27160084, 2016). "In cell lines derived from the same patient, EGFR and PODXL were expressed in the primary tumour cell line (SW480), but not in the metastatic derivative (SW620)." (PMID 27160084, 2016). "PODXL expression correlated neither with age, gender, stage, lymph-node ratio, tumor location (not shown), nor perivascular invasion." (PMID 26053486, 2015). "Overexpression of EZR, CLIC5 and PODXL genes was observed in nodular (N) and tumor (T) areas but not in non-tumor (NT) areas and controls (C)." (PMID 26135398, 2015). "The prognostic and predictive impact of membranous PODXL expression was similar when only its expression in the primary tumour was considered (data not shown)." (PMID 26028992, 2015). "We also show that the case-by-case expression of PODXL by mAb HES9 and pAb HPA 2110 do not correlate, even though their prognostic profile and association with clinicopathological parameters (except for tumour side) is similar." (PMID 25004935, 2014). "The results further support the clinical utility of PODXL as a biomarker for risk assessment in CRC, even in cases where no primary tumour is available for analysis, and irrespective of histopathological response to neoadjuvant treatment." (PMID 23819542, 2013). "The expression of PODXL in lymph node metastases can however provide prognostic information when no primary tumour is available for analysis." (PMID 23819542, 2013). "While all negative primary tumours had negative metastases, some PODXL positive primaries had a varying proportion of positive and negative metastatic lymph nodes." (PMID 23819542, 2013). "Since membranous staining of PODXL in most cases is seen in only a fraction of tumour cells, these tumours do not necessarily have the highest level of protein in total and overexpression of protein will not be reflected in high mRNA levels." (PMID 22769594, 2012). "In cohort 1, 137 (52.7%) tumours were negative for PODXL (score 0), 98 (37.7%) tumours displayed weak-moderate staining (score 1–2) and 25 (9.6%) tumours displayed high PODXL expression (score 3–4)." (PMID 22769594, 2012). "While the exact mechanisms by which PODXL promotes tumorigenesis is unknown, PODXL is suggested to contribute to budding of non-adhesive metastatic tumour nodules of ovarian and breast cancer." (PMID 38553472, 2024). "Why GAL3 may have opposing functionality in different tumor types is not known but may relate to whether PODXL presentation on the surface is required for tumorigenesis in all contexts." (PMID 36735782, 2023). "The results from this study further validate that membranous expression of PODXL is correlated to more aggressive tumours as it could not be demonstrated in non-invasive Ta-tumours." (PMID 28293425, 2017).
tumor (continued). "Finally, the results of clinical specimens and subcutaneous tumor xenograft samples further disclosed a negative correlation between miR-509-3-5P and PODXL." (PMID 28432273, 2017). "Interestingly, in our study, using the same cell lines, EGFR and PODXL were expressed in cells from the primary tumour, but not in the metastatic cell line." (PMID 27160084, 2016). "Kaplan-Meier analysis revealed significant associations of membranous PODXL expression with a reduced RFS (logrank p = 0.024) and OS (logrank p = 0.032) in I-type tumours and with a reduced RFS (logrank p = 0.022) but not OS in PB-type tumours." (PMID 26028992, 2015). "In cohort 2, PODXL expression was denoted as negative (score 0) in 198 (62.7%) tumours, weak-moderate (score 1–2) in 93 (29.5%) tumours and strong (score 3–4) in 25 (7.9%) tumours." (PMID 22769594, 2012). "In addition, if negative PODXL expression is to be used to select patients for surgery alone, it would be of importance to account for possible intratumor heterogeneity of PODXL expression, and thus take multiple biopsies from different parts of the tumor." (PMID 30355278, 2018). "However, no reaction was observed against mouse PODXL (data not shown), indicating that anti-PODXL antibodies might not affect the tumor angiogenesis or tumor microenvironment in mouse xenograft model." (PMID 29854293, 2018). "Furthermore, in patients with stage III disease in cohort 2, a trend towards the previously demonstrated benefit from adjuvant chemotherapy could be observed for patients with high tumour-specific PODXL expression, who had a similar DFS and OS as patients with PODXL-low tumours." (PMID 22769594, 2012). "PODXL, BCL7B, ARHGEF4, ITGB1, or tumor size were not included in the final model of the multivariate analysis." (PMID 31166991, 2019). "The results from this validation study provide further evidence that overexpression of PODXL protein is a predictor of poor prognosis in CRC, independent of tumour stage or other clinicopathological characteristics." (PMID 22769594, 2012). "Finally, we previously showed in xenograft experiments that the few remaining tumor cells following PODO447-ADC treatment are negative not only for the PODO447 glycoepitope, but also for the PODXL core protein." (PMID 38188285, 2023).